RUNX1 (RUNX family transcription factor 1)
Diseases named in the same sentence as RUNX1 in open-access papers (continued):
Sharing a sentence is not in itself a finding about the gene and the disease.
influenza infection (3 papers, 2022). "It is interesting to know whether the effects of RUNX1 on IAV infection is widely applied by other influenza virus strains." (PMID 35248104, 2022). "The importance of type I IFN is highlighted by recent studies demonstrating that the transcription factor RUNX1 facilitates influenza infection by dampening IFN responses and further underscored by identification of mutations in the type I IFN pathway in patients with severe influenza." (PMID 36061377, 2022). "Besides, as a transcription factor, RUNX1 is functionally associated with the immune system development and critical for inducing the production of many immune genes, which suggests RUNX1 may also be involved in other signaling pathways during influenza infection." (PMID 35248104, 2022). "Several studies applied genome-wide screens to identify the cellular factor involved in influenza infection and replication with different cells and different influenza strains, and only two groups who used H1N1 identified RUNX1 is one of the hundreds of targets." (PMID 35248104, 2022).
injury (3 papers, 2018 to 2025). Damage inflicted on the body as the direct or indirect result of an external force, with or without disruption of structural continuity. "Expression of Runx1 in neural precursor cells of the adult brain has been reported after traumatic brain injury." (PMID 29324888, 2018). "This suggests that RUNX1 modulation could be a novel therapeutic strategy for complications of retinal detachment and ocular trauma." (PMID 33257736, 2020).
lung diseases (3 papers, 2022 to 2024). "A core-DEG RUNX1, which culminated in a young male case, is also a mediator of inflammatory signaling and is associated with an inflammatory response in lung diseases." (PMID 38980578, 2024). "Our results also provided new insights into the role of RUNX1 in regulating immune function in pulmonary disease caused by IAV infection." (PMID 35248104, 2022).
lymphopenia (3 papers, 2011 to 2023). Reduction in the number of lymphocytes. "While some studies indicate that a decrease in RUNX1 signaling is indicative of increased cell death and diminished lymphocyte proliferation, which would correlate with late stage EVD’s characteristic lymphopenia, there is evidence that the opposite can also be true." (PMID 38035334, 2023).
Myocardial fibrosis (3 papers, 2021 to 2024). "Runx1 expression was also observed in cardiac fibroblasts along with genes contributing to myocardial fibrosis, such as POSTN, MEOX1 and FAP, and its expression was also negatively correlated to ejection fraction." (PMID 38862712, 2024). "In this study, we identified the cardioprotective effect of dihydrolycorine against adverse cardiac remodeling after MI and found that Runx1 is a critical regulator of myocardial fibrosis in the occurrence and development of adverse cardiac remodeling." (PMID 34725565, 2021). "Besides, RUNX1 inhibition mice showed decreased myocardial fibrosis area under TAC-induced condition." (PMID 37927796, 2023). "In order to illustrate the underlying molecular mechanisms of how RUNX1 regulates myocardial fibrosis, we examined whether the canonical Smad3-dependent TGF-β signaling could be activated by RUNX1 through luciferase reporter assay." (PMID 37927796, 2023). "As expected, the stimulation of Runx1 in MI rats failed to rescue myocardial fibrosis as measured by the expression of fibrotic and apoptotic genes and was unable to mitigate cardiomyocyte hypertrophy even after dihydrolycorine treatment." (PMID 34725565, 2021).
nonalcoholic fatty liver disease (3 papers, 2021 to 2022). "NAFLD, nonalcoholic fatty liver disease; NAFLD, nonalcoholic fatty liver disease; RUNX1, runt-related transcription factor 1; MoA, mechanism of action." (PMID 35740337, 2022).
ovarian tumor (3 papers, 2022 to 2023). "A conditional loss of Runx1 in the somatic cells of the ovary led to an increased prevalence of ovarian tumors in aged mice." (PMID 36430923, 2022). "We found that loss of Runx1 expression led to ovarian defects and increased risk of developing ovarian tumors in aged mice." (PMID 36430923, 2022). "The conditional knockout of Runx1 in somatic cells of mouse ovaries leads to abnormal follicle-like lesions and an increased risk of ovarian tumor development in aged mice." (PMID 36430923, 2022). "Using a conditional knockout of Runx1 in the somatic cells of the ovary, we discovered that Runx1 loss led to abnormal follicle-like lesions in young mice and appearance of ovarian tumors in aged mice." (PMID 36430923, 2022). "Blast in the GEPIA Cancer Genome database, RUNX1 was found to be overexpressed in 426 ovarian tumor tissues compared with normal ovarian tissues (n = 88)." (PMID 38057816, 2023). "Together, this study showed that Runx1 is required for normal granulosa cell differentiation and prevention of ovarian tumor development in mice." (PMID 36430923, 2022). "To investigate the potential role of Runx1 in ovarian tumor development, we developed a conditional knockout (KO) of Runx1 in the somatic cells of the ovary." (PMID 36430923, 2022). "By the age of 15 months, 27% of Runx1 KO mice presented macroscopic ovarian tumors composed of FOXL2+ granulosa cells." (PMID 36430923, 2022). "By the age of 15 months, 27% of Runx1 knockout (KO) females developed ovarian tumors that presented characteristics of granulosa cell tumors." (PMID 36430923, 2022). "In summary, we discovered that Runx1 is required for normal granulosa cell differentiation and prevention of ovarian tumor development in mice." (PMID 36430923, 2022). "Therefore, we suspected that Runx1 misexpression could result in either or both ovarian tumor types." (PMID 36430923, 2022). "We compared the bulk transcriptomes of hiPSCs, COV434 and KGN ovarian tumor cells, and sorted FOXL2+CD82+ granulosa-like cells from day 5 of a polyclonal differentiation with expression of our previously identified top TFs (NR5A1, TCF21, GATA4, and RUNX1)." (PMID 36803359, 2023).
pancreatic ductal adenocarcinoma (3 papers, 2017 to 2024). An infiltrating adenocarcinoma that arises from the epithelial cells of the pancreas. "However, the expression and function of RUNX1 in pancreatic ductal adenocarcinoma were still unclear." (PMID 29245924, 2017). "explored the YTHDC1/miR‐30d/RUNX1 pathway in pancreatic ductal adenocarcinoma, showing that YTHDC1 promotes miR‐30d biosynthesis, which targets RUNX1 to regulate SLC2A1 and HK1 expression, thereby inhibiting aerobic glycolysis." (PMID 39135292, 2024).
pulmonary fibrosis (3 papers, 2022 to 2025). Chronic progressive interstitial lung disorder characterized by the replacement of the lung tissue by connective tissue, leading to progressive dyspnea, respiratory failure, or right heart failure. "The role of RUNX1 in pulmonary fibrosis was elucidated by examining myofibroblast migration and collagen deposition." (PMID 40464702, 2025). "By focusing on screening genes associated with the RUNX1-binding promoter region and genes with the ability to promote ARDS-associated pulmonary fibrosis, we successfully found out that AKT3 is a downstream target gene of RUNX1." (PMID 38267920, 2024). "Double immunofluorescence results showed that TGF‐β1 or bleomycin increased the expression of RUNX1 and α‐SMA in MRC‐5 cells or mice lung tissue, suggesting that RUNX1 promotes the occurrence of pulmonary fibrosis." (PMID 40464702, 2025).
T-cell leukemia (3 papers, 2005 to 2019). A malignant disease of the T-lymphocytes in the bone marrow, thymus, and/or blood. "GATA2 and GATA1 are implicated at many (up to 90%) of the TAL1-bound sites in normal hematopoietic cells, and GATA3 along with ETS1 and RUNX1 can direct TAL1 binding when it is aberrantly expressed in T-cell leukemias." (PMID 25319994, 2014).
thyroid cancer (3 papers, 2021 to 2026). "In conclusion, our work reveals a metabolic-epigenetic axis underlying adaptive response to BRAFi and identifies RUNX1 as a novel oncogene in thyroid cancer." (PMID 41862440, 2026). "In addition, higher expression of RUNX1 correlates with poorer prognosis in thyroid cancer." (PMID 41862440, 2026). "This circRNA is formed by the circularization of exons 5–6 of the RUNX1 gene (hereafter referred to as circRUNX1), and no further studies have been reported on this circRNA in the field of thyroid cancer research." (PMID 33479208, 2021).
adenoma (2 papers, 2023 to 2024). A neoplasm arising from the epithelium. "Gal-3 levels further increase in the progression from PRL and ACTH-secreting adenomas to carcinomas; gene methylation plays a role in Gal-3 expression, and RUNX1 and RUNX2 transcription factors seem to target its gene directly, enhancing its expression." (PMID 37958702, 2023).
Alzheimer disease (2 papers, 2013 to 2022). A progressive, neurodegenerative disease characterized by loss of function and death of nerve cells in several areas of the brain leading to loss of cognitive function such as memory and language. "The transcription factor SPI1 (PU.1) is linked to Alzheimer’s disease likely by impacting neuroinflammatory response and was found to interact with its network neighbor RUNX1 in modulating gene expression." (PMID 36344995, 2022).
aortic stenosis (2 papers, 2016 to 2023). Aortic valve stenosis is a aortic valve disease caused by the incomplete opening of the aortic valve. "Deletion of chromosome 21q21.1–22.12 including the RUNX1 gene has been associated with multiple congenital anomalies and congenital heart defects including aortic stenosis." (PMID 27152866, 2016).
astrocytoma (2 papers, 2021 to 2023). "An Aml1/Runx1 protein accumulation, correlating to tumor aggressiveness has been reported in astrocytomas." (PMID 34440820, 2021). "A Runx1/Aml1 mRNA accumulation found in astrocytomas, correlates with tumor aggressiveness." (PMID 34440820, 2021). "Of these subtypes, RUNX1, RUNX2, and RUNX3 in astrocytoma is higher than that oligodendroglioma." (PMID 36321611, 2023).
bleeding disorders (2 papers, 2021). "Most of these genes are known to be involved in the manifestation of various clinical phenotypes, such as metabolic diseases (CPT1B and BLVRA); hemorrhagic diseases (RUNX1 and GP6); and neuronal disorders (KCNAB3, FAM179B, CCDC60, GRM6, and PRDM8), among others." (PMID 34440289, 2021).
bone cancer (2 papers, 2012 to 2022). A primary or metastatic malignant neoplasm affecting the bone or articular cartilage. "High-level amplification of TGFβ2 (1q41), CCND3 (6p21), WI-6509 (11qtel), SHGC-5557 (12ptel), TCL1A (14q32.1), CREBBP (16q13.3), HIC1 (17p13.3), THRA (17q11.2), AFM217YD10 (17qtel), LAMA3 (18q11.2), RUNX1 (21q22.3) and D22S543 (22q11), was commonly observed in aggressive bone tumors." (PMID 23199169, 2012).
brain cancer (2 papers, 2021 to 2022). A primary or metastatic malignant neoplasm affecting the brain. "Recently, a role for the transcriptional factor Runx1/Aml1 and the downstream ion channel genes in brain cancer development and progression has been suggested." (PMID 34440820, 2021).
brain tumor (2 papers, 2022 to 2023). "As it turned out, alternative splicing in ETV6-RUNX1 (identified in B-cell leukemia) is recapitulated in RUNX1 gene in normal GTEx blood samples, and alternative splicing in C11orf95-RELA (identified in Ependymoma, a brain tumor) is recapitulated in C11orf95 in normal GTEx brain samples." (PMID 37019972, 2023).
cleft palate (2 papers, 2018 to 2023). Cleft palate is a fissure type embryopathy that affects the soft and hard palate to varying degrees. "This subcluster is likely to be from the upper palate based on RUNX1 expression and could explain how EBF3 is a risk factor for cleft palate." (PMID 37532691, 2023). "The involvement of Stat3 modification in Runx1-Tgfb3 signaling may offer novel insights into the physiologic and pathophysiologic regulation of the palatal fusion and our study also clarifies potential therapeutic targets in the prevention and pharmaceutical intervention for cleft palate." (PMID 30046048, 2018).
colon adenocarcinoma (2 papers, 2021 to 2024). "PTGS2 expression positively correlated with RUNX1 level in colon adenocarcinoma (COAD) samples using the TCGA-COAD dataset." (PMID 38778047, 2024).
corneal disease (2 papers, 2021 to 2023). "On the contrary, the limbus and corneal epithelium show robust expression of RUNX1 and loss of RUNX1 occurs in the lesions of the human corneal disease tissues." (PMID 33462242, 2021). "With this method, we identified that the genes associated to our “curated corneal disease list” were significantly more likely to be bound by PAX6, FOXC1, RUNX1, and FOSL2." (PMID 37856539, 2023).
Duchenne muscular dystrophy (2 papers, 2015 to 2023). Duchenne muscular dystrophy (DMD) is a neuromuscular disease characterized by rapidly progressive muscle weakness and wasting due to degeneration of skeletal, smooth and cardiac muscle. "RUNX1 expression was found to be significantly increased in samples of muscle dystrophies, including mouse models of Duchenne muscular dystrophy (DMD) and amyotrophic lateral sclerosis (ALS), myopathy patients (including EDMD, DMD, AQM) and in cardiotoxin (CTX)-treated muscle." (PMID 26275053, 2015).
follicular lymphoma (2 papers, 2011 to 2016). Follicular lymphoma is a form of non-Hodgkin lymphoma characterized by a proliferation of B cells whose nodular structure of follicular architecture is preserved. "Nevertheless, it is tempting to speculate that in follicular lymphoma patients (which typically display BCL2 overexpression) with strong kidney infiltration ETV6/RUNX1 target genes could be involved." (PMID 26919255, 2016). "Importantly, the ETV6/RUNX1 fusion product and the antiapoptotic protein BCL2 cooperate in the development and progression of follicular lymphoma." (PMID 26919255, 2016).
gastric tumors (2 papers, 2010 to 2022). "The increased expression of the PPARδ target gene, Agptl4, the TGFβ-activated genes Runx1 and Runx2, and S100A8 and S100A9 in the gastric tumors indeed suggests a duality of function of both PPARδ and TGFβ signaling in gastric tumorigenesis." (PMID 21318167, 2010).
glomerulonephritis (2 papers, 2016 to 2019). A renal disorder characterized by damage in the glomeruli. "BCL2 transgenic and ETV6/RUNX1;BCL2 double transgenic mice develop a glomerulonephritis phenotype over time, which was displayed by staining of kidney sections." (PMID 31404120, 2019). "Our study therefore demonstrates a novel cooperative activity of ETV6/RUNX1 and BCL2 for glomerulonephritis and lymphoma development." (PMID 26919255, 2016). "In addition, as the ETV6/RUNX1 fusion is frequently observed in newborn children, individual autoimmune or immune complex glomerulonephritis patients harboring the ETV6/RUNX1 fusion (in plasma B cells) could exist exhibiting an aggravated glomerulonephritis phenotype." (PMID 26919255, 2016).
Hepatic steatosis (2 papers, 2019 to 2021). Steatosis is a term used to denote lipid accumulation within hepatocytes. "In order to add new knowledge about the role of RUNX1 in hepatic steatosis, we then subclassified our patients with MO and NAFLD into SS (n = 24) and NASH (n = 17)." (PMID 34063472, 2021). "Therefore, we intended to deepen our knowledge about the implications of the RUNX1 expression in liver steatosis and related inflammation." (PMID 34063472, 2021).
Insulin resistance (2 papers, 2022 to 2025). Increased resistance towards insulin, that is, diminished effectiveness of insulin in reducing blood glucose levels. "In the liver, CBFA2/RUNX1 partner transcriptional co-repressor 3 (CBFA2T3) can be activated by PPARα, influencing glucose tolerance and insulin resistance in mice." (PMID 39996752, 2025).
lymph node metastasis (2 papers, 2019 to 2023). "High expression of RUNX1 was significantly associated with gender (p = 0.003), clinical stage (p < 0.001), tissue infiltration (p < 0.001), lymph node metastasis (p = 0.037) and histological grade (p < 0.001)." (PMID 31592165, 2019). "RUNX1 expression positively correlated with histologic grade (r = 0.388), tumor size (r = 0.319), and lymph node metastasis (r = 0.304)." (PMID 37697370, 2023).
morbid obesity (2 papers, 2021 to 2023). An excess of body weight, normally defined as an individual with a body mass index greater than 35 or a body weight greater than one hundred percent of ideal body weight. "The aim of this study was to analyze RUNX1 mRNA hepatic and jejunal abundance in women with morbid obesity (MO) and NAFLD." (PMID 34063472, 2021). "Therefore, the main aim of this study was to analyze the relative mRNA hepatic abundance of RUNX1 in women with morbid obesity (MO) and NAFLD, with different degrees of liver damage." (PMID 34063472, 2021). "These facts suggest that RUNX1 may have a protective role in NAFLD progression in patients with morbid obesity." (PMID 34063472, 2021).
muscle atrophy (2 papers, 2022 to 2025). The loss of muscle tissue due to inactivity or disease. "Given its strong association with skeletal muscle atrophy, RUNX1 was selected for further investigation to determine its expression patterns across different cell populations." (PMID 40917776, 2025). "The findings demonstrated that RUNX1 expression was upregulated in type I, type IIa, and macrophage subclusters, underscoring its potential role in mediating denervation-induced muscle atrophy." (PMID 40917776, 2025).
oral cancer (2 papers, 2014 to 2022). "In addition, work from Tumbar’s laboratory has shown that RUNX1 overexpression leads to STAT3 activation and is necessary for skin and oral cancer growth." (PMID 24967588, 2014).
pancreatic adenocarcinoma (2 papers, 2017 to 2022). "Here, we show that RUNX1 is highly expressed in pancreatic adenocarcinoma tissues and knocking down of RUNX1 attenuated aggressiveness in pancreatic cell lines." (PMID 29245924, 2017).
preeclampsia (2 papers, 2021 to 2026). Preeclampsia is a hypertensive disorder of pregnancy that is characterized by new-onset hypertension with proteinuria presenting after 20 weeks of gestation, and depending on mild or severe forms may initially present with severe headache, visual disturbances, and hyperreflexia. "Several reports have demonstrated that RUNX1 and YAP1 have active roles in preeclampsia, but these genes might be novel target for GDM." (PMID 33890634, 2021).
prion disease (2 papers, 2014 to 2020). A transmissible disease that is caused by a protein that is able to induce abnormal folding of normal cellular proteins, leading to characteristic spongiform brain changes, which are associated with neuronal loss without an inflammatory response. "The transcription factors RUNX1 and IRF8, involved in the proliferation and lineage commitment of microglia, were found to be upregulated in animals with prion disease, with no differential effect of the CCR2−/− background." (PMID 24648328, 2014).
psoriatic arthritis (2 papers, 2023). Joint inflammation associated with psoriasis. "On the other hand, polymorphisms in IL23R, TNFAIP3, PTPN22 (tyrosine-protein phosphatase non-receptor type 22), IL12B, RUNX1 (CD8-lymphocyte activation and differentiation), IL13, KIR (killer-cell immunoglobulin-like receptor), and MAGI1 genes have shown association with psoriatic arthritis." (PMID 37628670, 2023).